NTN3 (netrin 3)
Description:
Netrins control guidance of CNS commissural axons and peripheral motor axons.
Synonyms: NTN2L
Tractability: Antibody: UniProt places it where antibodies can reach, with medium confidence; UniProt predicts a signal peptide or a membrane-spanning region; its Gene Ontology location is reachable by antibodies, with medium confidence.
Gene: Protein-coding gene on chromosome 16 (2,471,297 to 2,474,145, forward strand). Ensembl gene ENSG00000162068.
Subcellular location: Secreted, extracellular space, extracellular matrix
Pathways (Reactome):
Developmental Biology: Myogenesis
Gene Ontology:
Molecular function: protein binding; DNA-binding transcription factor activity, RNA polymerase II-specific; RNA polymerase II cis-regulatory region sequence-specific DNA binding; signaling receptor binding
Biological process: axon guidance; regulation of transcription by RNA polymerase II; axonogenesis
Cellular component: RNA polymerase II transcription regulator complex; cytoplasm; extracellular region; Golgi apparatus
Genetic constraint (gnomAD): Loss-of-function variants: 47 observed, 34.33 expected, observed/expected ratio (o/e) 1.37, 90% interval 1.08 to 1.74. The synonymous counts are far from expectation, so gnomAD's model fits this gene poorly and the ratio says little. Missense variants: 882 observed, 725.91 expected, observed/expected ratio (o/e) 1.22, 90% interval 1.15 to 1.28. Synonymous variants: 385 observed, 308.5 expected, observed/expected ratio (o/e) 1.25, 90% interval 1.15 to 1.36.
Homologues: Orthologues: chimpanzee NTN3 (99% identical), macaque NTN3 (98% identical), pig NTN3 (92% identical), dog NTN3 (91% identical), rat Ntn3 (88% identical), mouse Ntn3 (87% identical), guinea pig NTN3 (85% identical), rabbit NTN3 (57% identical), zebrafish ntn2 (56% identical), tropical clawed frog ntn3 (55% identical), Drosophila melanogaster NetA (47% identical), Caenorhabditis elegans unc-6 (44% identical), and 1 more. Paralogues in human: NTN1 (55% identical), NTN5 (37% identical), LAMC1 (33% identical), LAMB2 (32% identical), LAMC3 (31% identical), LAMA5 (28% identical), LAMB1 (28% identical), LAMA3 (28% identical), LAMB4 (28% identical), LAMA2 (27% identical), LAMA1 (26% identical), NTN4 (26% identical), and 15 more.
Diseases named in the same sentence as NTN3 in open-access papers:
NTN3 is named in the same sentence as 14 diseases in open-access papers, as found by Europe PMC text mining. Sharing a sentence is not in itself a finding about the gene and the disease. The quoted sentences say what the papers report.
neuroblastoma (2 papers, 2022 to 2024). Neuroblastoma (NB) is the most common solid, extracranial childhood tumor. "Recent work has also implicated Netrin-3 in promoting SCLC and neuroblastoma." (PMID 39172021, 2024). "Further exploitation of dependence receptor stimulation for cancer cell killing is undertaken by targeting Netrin-3, an understudied member of the Netrin ligand family in cancer, whose expression correlates with cancer aggressiveness in neuroblastoma and small cell lung cancer (SCLC) (Gibert team)." (PMID 35883457, 2022). "Interestingly, team Gibert showed that Netrin-3 expression correlates with cancer aggressiveness and poor patient prognosis for both neuroblastoma and small cell lung cancer (SCLC)." (PMID 35883457, 2022).
breast carcinoma (1 paper, 2020).
glioblastoma (1 paper, 2011). The most malignant astrocytic tumor (WHO grade IV). "The glioblastoma-derived cell lines tested express either netrin-1 (U343, U373) or netrin-3 (U87)." (PMID 21980448, 2011). "We determined that the human glioblastoma cell lines U87, U343, and U373 all express neogenin, UNC5 homologues, and netrin-1 or netrin-3, but only U87 cells express DCC." (PMID 21980448, 2011).
metastatic disease (1 paper, 2025). "The upregulation of genes encoding matrix associated factors including proteases and cell adhesion molecules such as ADAM12, NTN3, LRRC15, CDH17, PCDH19, VTN highlighted the relevance of the tumor microenvironment and cell–cell and cell–matrix interaction for progression to metastatic disease." (PMID 41402347, 2025).
prostate carcinoma (1 paper, 2020). A carcinoma that arises from epithelial cells of the prostate gland. "Bicalutamide is an FDA approved drug for the treatment of prostate cancer, and is also sensitive to NTN3." (PMID 32251318, 2020). "For example, NTN3 is regulated by AR and EZH2 in prostate cancer, and also acts in the activation of the hormone ER pathway." (PMID 32251318, 2020). "Highly expressed NTN3 and NTNG2 cells are sensitive to these drugs, suggesting NTN3 and NTNG2 may be involved in N-Myc-related pathways and affect androgen-independent prostate cancer development." (PMID 32251318, 2020). "Here, we found that NTN3 transcription is positively regulated by both EZH2 and AR in prostate cancer (r = 0.2297 and 0.2863, respectively), suggesting that NTN3 may play a oncogenic role in prostate cancer." (PMID 32251318, 2020).
retinoblastoma (1 paper, 2024). A malignant tumor that originates in the nuclear layer of the retina. "Examination of RNA-Seq data from retinoblastoma and SCLC revealed up-regulation of multiple UNC5 and NTN members following forced YAP expression, including UNC5B/C/D and NTN1, but not NTN3." (PMID 39172021, 2024).
cancer (5 papers, 2020 to 2025). A tumor composed of atypical neoplastic, often pleomorphic cells that invade other tissues. "However, the hot spot mutation P201Qfs*15 of NTN3 was identified in three patients, each with a different cancer (ESCA, STAD, UCEC), and encodes a truncated protein." (PMID 32251318, 2020). "The team showed that Netrin-3 has a high specificity for SCLC cells and its therapeutic targeting using a blocking antibody reduces cancer growth." (PMID 35883457, 2022). "Consistent with prior work showing that Netrin-3 promotes SCLC, we found that Netrin-1 but not Netrin-3 was induced following forced YAP expression in this cancer." (PMID 39172021, 2024). "Because high expression of NTN3 and NTNG1 is sensitive to these compounds, we can speculate that NTN3 and NTNG1 may be involved in the mesenchymal state of cancer." (PMID 32251318, 2020).
tumor (4 papers, 2019 to 2025). "Nevertheless, additional studies are needed to understand the NTN3 function and possible isoforms present with respect to tumor biology." (PMID 30923634, 2019). "The relative mRNA expression of NTN3 has been quantified in tumor and normal prostate tissue." (PMID 30923634, 2019). "Highly expressed NTN3, NTN5, and NTNG1 are correlated and sensitive to these three drugs, suggesting that the netrin family may be involved in tumor metabolism." (PMID 32251318, 2020). "The high expression of NTN1, NTN3, and NTNG1 is also sensitive to MS-275 (HDAC inhibitor), RG-108 (DNA methyltransferase inhibitor), and CUDC-101 (HDAC inhibitor, EGFR inhibitor, and HER2 inhibitor), which inhibit tumor by affecting epigenesis." (PMID 32251318, 2020).
NTN3 also shares sentences with these, for which no sentence is quoted: Alzheimer disease (1 paper); amyloid (1); colorectal cancer (1); diabetic (1); Pain (1); small cell lung carcinoma (1).